SUSD5 (sushi domain containing 5)
Synonyms: KIAA0527
Tractability: Antibody: UniProt predicts a signal peptide or a membrane-spanning region. PROTAC: ubiquitination databases record sites on it.
Gene: Protein-coding gene on chromosome 3 (33,150,043 to 33,218,810, reverse strand). Ensembl gene ENSG00000173705.
Subcellular location: Membrane
Subcellular location (Human Protein Atlas): Golgi apparatus; Vesicles
Gene Ontology:
Molecular function: hyaluronic acid binding
Biological process: Notch signaling pathway; cell adhesion
Cellular component: membrane
Genetic constraint (gnomAD): Loss-of-function variants: 24 observed, 20.98 expected, observed/expected ratio (o/e) 1.14, 90% interval 0.83 to 1.6. The upper end of that interval is the gene's LOEUF score, 1.6, which puts it in group 6 of 6, group 1 being the genes least tolerant of losing a copy. Missense variants: 692 observed, 729.06 expected, observed/expected ratio (o/e) 0.95, 90% interval 0.89 to 1.01. Synonymous variants: 279 observed, 297.78 expected, observed/expected ratio (o/e) 0.94, 90% interval 0.85 to 1.03.
Homologues: Orthologues: chimpanzee SUSD5 (98% identical), macaque SUSD5 (95% identical), pig SUSD5 (79% identical), dog SUSD5 (78% identical), guinea pig SUSD5 (70% identical), rat Susd5 (69% identical), mouse Susd5 (68% identical), rabbit SUSD5 (66% identical), zebrafish susd5 (29% identical).
Diseases named in the same sentence as SUSD5 in open-access papers:
SUSD5 is named in the same sentence as 6 diseases in open-access papers, as found by Europe PMC text mining. Sharing a sentence is not in itself a finding about the gene and the disease. The quoted sentences say what the papers report.
gastric cancer (1 paper, 2024). A primary or metastatic malignant neoplasm involving the stomach. "The study identified a panel of four mRNAs (AGTR1, DNER, EPHA7, and SUSD5) significantly upregulated in recurrent gastric cancer tissues compared to non‐recurrent tissues." (PMID 39556695, 2024). "A novel liquid biopsy method using a 4‐mRNA biomarker panel (AGTR1, DNER, EPHA7, SUSD5) improves early detection of recurrence in locally advanced gastric cancer." (PMID 39556695, 2024).
tumor (1 paper, 2024). "We performed in vivo knockdown experiments targeting AGTR1, DNER, EPHA7, and SUSD5 in BALB/c nude mice to investigate the effects of these recurrence mRNA panel genes on GC tumor growth and metastasis." (PMID 39556695, 2024). "Mutational profiling results indicated that the overall tumor mutation burden and the mutation frequency of the gene TTN were higher in the low expression group of AGTR1, SUSD5, and EPHA7, while the opposite trend was observed for DNER (Supporting Informmation)." (PMID 39556695, 2024).
SUSD5 also shares sentences with these, for which no sentence is quoted: cancer (1 paper); colorectal cancer (1); lung carcinoma (1); melanoma (1).